PBX2 (PBX homeobox 2)
Description:
Transcriptional activator that binds the sequence 5'-ATCAATCAA-3'. Activates transcription of PF4 in complex with MEIS1.
Synonyms: G17; HOX12; PBX2MHC
Tractability: PROTAC: ubiquitination databases record sites on it; its protein half-life has been measured.
Gene: Protein-coding gene on chromosome 6 (32,184,733 to 32,190,202, reverse strand). Ensembl gene ENSG00000204304.
Subcellular location: Nucleus
Subcellular location (Human Protein Atlas): Nucleoplasm
Gene Ontology:
Molecular function: DNA-binding transcription activator activity, RNA polymerase II-specific; DNA-binding transcription factor binding; protein binding; RNA polymerase II transcription regulatory region sequence-specific DNA binding; DNA-binding transcription factor activity, RNA polymerase II-specific; RNA polymerase II cis-regulatory region sequence-specific DNA binding; chromatin binding; DNA binding; DNA-binding transcription factor activity
Biological process: positive regulation of transcription by RNA polymerase II; animal organ morphogenesis; brain development; embryonic organ development; eye development; neuron development; regulation of DNA-templated transcription
Cellular component: nucleoplasm; nucleus; chromatin; transcription regulator complex
Genetic constraint (gnomAD): Loss-of-function variants: 10 observed, 42.48 expected, observed/expected ratio (o/e) 0.24, 90% interval 0.14 to 0.4. The synonymous counts are far from expectation, so gnomAD's model fits this gene poorly and the ratio says little. Missense variants: 367 observed, 520.03 expected, observed/expected ratio (o/e) 0.71, 90% interval 0.65 to 0.77. Synonymous variants: 149 observed, 191.18 expected, observed/expected ratio (o/e) 0.78, 90% interval 0.68 to 0.89.
Homologues: Orthologues: chimpanzee PBX2 (100% identical), macaque PBX2 (99% identical), dog PBX2 (99% identical), guinea pig PBX2 (99% identical), pig PBX2 (99% identical), rabbit PBX2 (99% identical), rat Pbx2 (98% identical), mouse Pbx2 (98% identical), tropical clawed frog pbx2 (74% identical), Drosophila melanogaster exd (61% identical), Caenorhabditis elegans ceh-20 (46% identical), Caenorhabditis elegans ceh-60 (18% identical), and 4 more. Paralogues in human: PBX3 (76% identical), PBX1 (76% identical), PBX4 (59% identical), MEIS2 (22% identical), MEIS1 (20% identical), MEIS3 (19% identical), MEIS3P2 (18% identical), PKNOX2 (17% identical), PKNOX1 (14% identical), TGIF1 (10% identical), TGIF2 (9% identical), TGIF2LX (7% identical), and 1 more.
Diseases named in the same sentence as PBX2 in open-access papers:
PBX2 is named in the same sentence as 35 diseases in open-access papers, as found by Europe PMC text mining. Sharing a sentence is not in itself a finding about the gene and the disease. The quoted sentences say what the papers report.
lung carcinoma (5 papers, 2021 to 2023). "We found that PBX2 linked hypertension, diabetes, obesity, and lung cancer with each other." (PMID 36685671, 2023). "MiR‐1915–3 directly bound to the 3'UTR of PBX2 mRNA, subsequently downregulating its expression in lung cancer cells." (PMID 35068042, 2022). "PBX2 could mediate the negative regulation of miR‐1915‐3p on apoptosis in lung cancer." (PMID 35068042, 2022). "PBX2 could induce apoptosis in lung cancer, indicating its anti‐tumoural role." (PMID 35068042, 2022). "In addition, miR-1915-3p could impair etoposide-induced apoptosis, thereby increasing chemoresistance via downregulating DRG2 and PBX2 in lung cancer cell lines (NCI-H441 and NCI-H1650)." (PMID 34774019, 2021). "In lung cancer cells, miR-1915 is suggested as an antiapoptotic non-coding RNA by targeting DRG2/PBX2." (PMID 34680382, 2021).
leukemia (3 papers, 2007 to 2022). A malignant (clonal) hematologic disorder, involving hematopoietic stem cells and characterized by the presence of primitive or atypical myeloid or lymphoid cells in the bone marrow and the blood. "The immunological signature enrichment revealed the presence of genes, such as BRD3, PBX2, and WNT5B, involved in HSPC proliferation, self-renewal, and differentiation, found deregulated in leukemia." (PMID 31109375, 2019).
melanoma (3 papers, 2013 to 2022). A malignant, usually aggressive tumor composed of atypical, neoplastic melanocytes. "In the metastatic melanoma cell line, both mRNA and protein expression analysis has shown that Pbx2 expression was elevated when compared to Pbx1, Pbx3, and Pbx4." (PMID 33402862, 2020). "The analysis of the PBX family mRNAs (PBX1 to 4) in the metastatic melanoma cell line A375M confirmed PBX2 principal expression (top)." (PMID 23400877, 2013). "To demonstrate that the HOXB7/PBX2 dimer can activate the transcription of miR-221&222 in melanoma, we selected the Me1402/R cell line for HOXB7 transient over-expression (right)." (PMID 23400877, 2013). "The potential value of the HOXB7/PBX2→miR-221&222→c-FOS pathway suggests the disruption of the HOXB7/PBX2 complexes, miR-221&222 inhibition or their combination as innovative therapeutic approaches in melanoma." (PMID 23400877, 2013). "Finally, western blot analysis showed a significant higher level of PBX2 in melanoma cell lines respect to normal melanocytes." (PMID 23400877, 2013). "In view of the requirement of HOX cofactors, such as PBX proteins, for HOXB7 oncogenic activity, we measured the levels of PBX1 and PBX2 proteins in melanoma cell lines, representative of early and advanced stages, showing that PBX2 protein was more abundant than PBX1 (bottom)." (PMID 23400877, 2013). "PBX2 formed a dimer with HOXB7, and the dimer decreased the expression of c‐FOS by upregulated miR‐221 and miR‐222 in melanoma cells." (PMID 35068042, 2022). "Our findings, besides suggesting the potential therapeutic of HXR9 or its derivatives in malignant melanoma, suggest the disruption of the HOXB7/PBX2 complexes, miR-221&222 inhibition or even better their combination, as innovative therapeutic approaches." (PMID 23400877, 2013). "HXR9 treatment results in the downregulation of miR-221&222 in human melanoma cells as a consequence of HOXB7/PBX2 heterodimer disruption and the subsequent degradation of HOXB7 and PBX2 proteins." (PMID 23400877, 2013).
breast carcinoma (2 papers, 2022 to 2023). "The protein expression of RAD50, RAD52, and PBX2 was confirmed in breast cancer cell lines MCF7, AU565, BT474, and MDA453 and immortalized breast epithelial cell line MCF10A." (PMID 37445737, 2023). "We sought to identify immune cell types that significantly (two-sample t-tests; p < 0.05) differed in activity across breast cancer patient groups with high and low expression of RAD52 and PBX2 linked to their survival outcomes." (PMID 37445737, 2023). "PBX2 was underexpressed in luminal A breast cancer MCF7 and TNBC MDA453 cells but was overexpressed in Her2-positive AU565 and BT474 cells, compared with normal breast MCF10A cells." (PMID 37445737, 2023). "It has been showed that the overexpression of PBX2 increases the tumorigenic properties of SkBr3 breast cancer cell line when transfected with HoxB7." (PMID 36338974, 2022). "RAD52 and PBX2 had differential protein expression among breast cancer stages." (PMID 37445737, 2023). "The protein expression of RAD52, RAD50, PBX2, MAP2K2 (MEK2), and S100P was also validated with immunohistochemistry in invasive breast cancer tumor tissues." (PMID 37445737, 2023). "The protein expression of FGF-2, RAD52, RAD50, PBX2, MAP2K2 (MEK2), and S100P was also validated with immunohistochemistry in invasive breast cancer tumor tissues." (PMID 37445737, 2023). "The protein expression of PBX2 and RAD52 assessed with immunohistochemistry were prognostic of breast cancer survival outcomes." (PMID 37445737, 2023). "The entire mechanism involving FGF2, PBX1/PBX2, and HOXB7/HOXB8 in breast cancer tumorigenesis is not clear." (PMID 37445737, 2023).
glioma (2 papers, 2021 to 2024). A benign or malignant brain and spinal cord tumor that arises from glial cells (astrocytes, oligodendrocytes, ependymal cells). "MiR-320e has been identified as a potential therapeutic target up-regulating the PBX2/Raf-1/MAPK axis in glioma." (PMID 38455766, 2024). "CircTLK1 mediated by PBX2 regulates JAK/STAT signaling to promote glioma development via the miR-452-5p/SSR1 axis." (PMID 34721518, 2021). "Taken together, our findings show that circTLK1 mediated by PBX2 activates JAK/STAT signaling to promote glioma progression through the miR-452-5p/SSR1 pathway." (PMID 34721518, 2021). "Although we partially demonstrated the existence of the novel PBX2/circTLK1/miR-452-5p/SSR1 axis in glioma progression, this will require extensive investigation." (PMID 34721518, 2021). "Investigation of the mechanisms upstream and downstream of circTLK1 revealed that circTLK1 mediated by PBX2 aggravates glioma progression by activating JAK/STAT signaling via the miR-452-5p/SSR1 axis." (PMID 34721518, 2021). "The findings of this study revealed that circTLK1 mediated by PBX2 regulated JAK/STAT signaling to promote glioma development by facilitating miR-452-5p/SSR1." (PMID 34721518, 2021). "By utilizing the JASPAR dataset, ChIP, and luciferase reporter assays, we identified that PBX2 could bind to the circTLK1 promoter and mediate circTLK1 expression in glioma cells." (PMID 34721518, 2021). "Our results suggest that PBX2 might be at functional upstream regulator of circTLK1 in glioma cells." (PMID 34721518, 2021). "Our results indicated that circTLK1 expression in glioma cells could be mediated by the transcriptional regulator PBX2." (PMID 34721518, 2021). "Moreover, we investigated the upstream regulator of circTLK1 and found that circTLK1 expression in glioma cells could be regulated by the transcriptional factor PBX2." (PMID 34721518, 2021).
agranulocytosis (1 paper, 2022). "This analysis revealed top genes, such as NOTCH4, MICA, TRIM27, PBX2, and FKBPL, as enriched in GWAS of schizophrenia, CLZ-induced agranulocytosis/granulocytopenia in treatment-resistant schizophrenia, and bipolar disorder among other psychiatric and non-psychiatric conditions." (PMID 35664466, 2022).
autism spectrum disorder (1 paper, 2025). A spectrum of developmental disorders that includes autism, and Asperger syndrome. "The next is PBX2 (brain-wide MTSG P-value: 1.84 × 10-13, single tissue P-value: 1.0), which was mapped by three variants from a GWAS study for autism spectrum disorder or SCZ." (PMID 40690510, 2025).
chronic lymphocytic leukaemia (1 paper, 2024). "This integrative analysis identified genes whose dysregulation may explain the links between JIA and associated traits, such as autoimmune/inflammatory diseases (genes at 6p22.1 locus), Hodgkin lymphoma (genes at 6p21.3 [FKBPL, PBX2, AGER]), and chronic lymphocytic leukemia (BAK1)." (PMID 39175752, 2024). "Notably, in addition to HLA class II genes (which might contribute to chronic inflammation), we found a distinct association between JIA and Hodgkin lymphoma through a set of genes in 6p21.3 (FKBPL, PBX2, AGER); and chronic lymphocytic leukaemia through the BAK1 gene." (PMID 39175752, 2024).
embryonal carcinoma (1 paper, 2022). A non-seminomatous malignant germ cell tumor characterized by the presence of large germ cells with abundant cytoplasm resembling epithelial cells, geographic necrosis, high mitotic activity, and pseudoglandular and pseudopapillary structures formation. "The expression of PBX1, PBX2, and PBX3 was upregulated during endodermal and neuronal differentiation of embryonal carcinoma P19 cells in a RAR‐dependent subtype‐unspecific manner following RA treatment." (PMID 35068042, 2022).
endometrial cancer (1 paper, 2008). Primary or metastatic malignant neoplasm involving the endometrium (mucous membrane that lines the endometrial cavity). "In addition, PBX2 and HOXA10 interactions with EMX2 were demonstrated in endometrial cancer cell lines." (PMID 18973687, 2008).
esophageal squamous cell carcinoma (1 paper, 2021). Esophageal squamous cell carcinoma (ESCC) is a type of esophageal carcinoma (EC) that can affect any part of the esophagus, but is usually located in the upper or middle third. "PBX2 genes are found to be abnormally expressed in different cancer types, including esophageal squamous cell carcinoma (ESCC), gastric carcinoma (GC), gingival squamous cell carcinoma, along with non-small cell lung carcinoma (NSCLC)." (PMID 33535170, 2021).
Ewing sarcoma (1 paper, 2022). A small round cell tumor that lacks morphologic, immunohistochemical, and electron microscopic evidence of neuroectodermal differentiation. "Knockdown of GPR64 decreased the expression of PBX2 in Ewing sarcomas cells." (PMID 35068042, 2022).
gastric cancer (1 paper, 2021). A primary or metastatic malignant neoplasm involving the stomach. "These experiments suggest that the positively expression of HOXA6 is associated with PBX2 expression in gastric cancer." (PMID 33535170, 2021). "For determining the synergistic effect of HOXA6 and PBX2 on promoting gastric cancer cell invasion and migration, we examined the effect of HOXA6 or PBX2 overexpression or knockdown with siRNA." (PMID 33535170, 2021). "Moreover, HOXA6 physically interacts with PBX2, and the coexpression of HOXA6 and PBX2 promotes gastric cancer cell migration and invasion." (PMID 33535170, 2021).
invasive breast carcinoma (1 paper, 2023). A carcinoma that infiltrates the breast parenchyma. "PBX2 and RAD52 protein expression levels in IHC are prognostic in invasive breast cancer patients." (PMID 37445737, 2023).
lupus (1 paper, 2020). "The lupus epistasis network also contains a significant interaction between HLA-DOB and PBX2, which are both located within the MHC class II region on chromosome 6." (PMID 32774345, 2020).
metastatic melanoma (1 paper, 2013). A melanoma that has spread from its primary site to another anatomic site. "To test whether these putative BSs were truly functional, we performed a series of promoter luciferase assays by utilizing the highly transfectable 293FT and the metastatic melanoma A375M cell lines, endogenously expressing both HOXB7 and PBX2." (PMID 23400877, 2013).
Nephroblastoma (1 paper, 2023). An embryonal neoplasm characterized by the presence of epithelial, mesenchymal, and blastema components. "There was research which found that MEIS1 and PBX2 overexpressed in nephroblastomas." (PMID 36836180, 2023).
rectal cancer (1 paper, 2012). A primary or metastatic malignant neoplasm that affects the rectum. "Copy number increase of EFNA1 (1q22), PTGS2 (1q31.1), KDM5B (1q32.1), ESRRG (1q41), KIFC1 (6p21.32), PBX2 (6p21.32) and SOX4 (6p22.3) were only detected in rectal cancer in array CGH." (PMID 23158542, 2012).
rheumatic diseases (1 paper, 2025). "It has been discovered that some of these genes (C2, BX511262.2, PRRC2A, BAG6, PBX2, GPSM3, NELFE and AIF1) are significant genetic targets shared by MetS and multiple rheumatic diseases." (PMID 39789419, 2025).
T-cell leukemia (1 paper, 2013). A malignant disease of the T-lymphocytes in the bone marrow, thymus, and/or blood. "PBX2 is a gene involved in B-cell and certain T-cell leukemias." (PMID 23326239, 2013).
tumor (7 papers, 2020 to 2025). "The overexpression of Pbx2 is associated with tumor size, stage, and metastasis, as well as a high expression of the valosin-containing protein (VCP) in GSCC cells." (PMID 33402862, 2020). "The missense mutation of the PBX2 gene could contribute to tumor progression by controlling the gene regulatory networks involved in cell proliferation, apoptosis, cell cycle, epithelial-mesenchymal transition (EMT), invasion, and metastasis, as well as the stemness of cancer cells." (PMID 35742955, 2022). "PBX2, known to drive tumor progression by modulating oncogenes and non‐coding RNAs, had unclear direct targets in HNSCC." (PMID 40270464, 2025). "PBX2 is postulated to play an important part in the upregulation of tumor-correlation protein expression." (PMID 33535170, 2021). "These consistent findings suggest that the expression of PBX2, PRMT1, SMARCC1, and IGF2BP2 in tumor tissues could serve as reliable diagnostic markers for HNSCC due to their high sensitivity and specificity." (PMID 40270464, 2025). "Moreover, the downregulation of Gpr64 leads to the downregulation of tumor growth and metastasis, as well as the upregulation of Pbx2, Slit2, and Mbd2." (PMID 33402862, 2020). "Tumor suppressor roles of PBX2 have also been demonstrated in sarcoma." (PMID 33402862, 2020). "Clinical data analysis revealed a strong correlation between high levels of PBX2, PRMT1, SMARCC1, and IGF2BP2 with poor prognosis and tumor progression in HNSCC patients." (PMID 40270464, 2025). "Next, we detected the expression of HOXA6 and PBX2 in 23 gastric mucosa tumor tissue specimens and adjacent nontumor tissue by IHC staining." (PMID 33535170, 2021). "Among them, PBX1, PBX2, PBX3 and PBX4, which are members of the PBX gene family, may be involved in tumor cell development." (PMID 33535170, 2021). "HOXA6 played a crucial part in tumor metastasis and invasion, we questioned whether HOXA6 synergizes with PBX2 to promote GC metastasis." (PMID 33535170, 2021). "Additionally, the up-regulated PBX2 level is identified as the factor to independently predict the poor prognosis of ESCC and GC, and PBX2 may suppress cell apoptosis to enhance tumor development." (PMID 33535170, 2021).
cancer (6 papers, 2021 to 2025). A tumor composed of atypical neoplastic, often pleomorphic cells that invade other tissues. "Pearson correlation analysis showed that HOXA6 level showed positive association with PBX2 level within cancer tissues." (PMID 33535170, 2021). "Furthermore, CDC42BPB, CKAP4, KMT2D, and PBX2 have been shown to be strongly associated with the development of certain cancers." (PMID 40608007, 2025). "Recent studies suggested that PBX2 dysregulation is closely associated with cancer progression." (PMID 36499314, 2022). "PBX2 knockdown is discovered to down-regulate the colony formation ability in vitro and the tumorigenicity in vivo within cancer cells." (PMID 33535170, 2021). "Similarly, we observed an association of HOXA9 with PBX1, PBX2, PBX3, and MEIS1 in all 10 cancer types except for STAD." (PMID 38904676, 2024). "In addition, HOXA6 and PBX2 levels were markedly up-regulated within GC samples compared with the matched non-carcinoma samples." (PMID 33535170, 2021). "Analysis of the HOXA9 gene revealed a positive correlation with PBX1, PBX2, PBX3, and MEIS1 in all cancer types except for STAD among the 11 studied genes, suggesting enhanced binding of HOXA9 to the promoter region of target genes." (PMID 38904676, 2024).
PBX2 also shares sentences with these, for which no sentence is quoted: asthma (2 papers); acute leukemia (1); bipolar disorder (1); diabetes (1); granulocytopenia (1); Hodgkins lymphoma (1); Hypertension (1); invasive carcinoma (1); non-small cell lung carcinoma (1); Obesity (1); orofacial clefting (1); schizophrenia (1); squamous cervical cancer (1).